GH1 (growth hormone 1)
Description:
Plays an important role in growth control. Its major role in stimulating body growth is to stimulate the liver and other tissues to secrete IGF1. It stimulates both the differentiation and proliferation of myoblasts. It also stimulates amino acid uptake and protein synthesis in muscle and other tissues.
Synonyms: GH; GH-N; hGH; GHN; hGH-N; GHB5; IGHD1A; IGHD1B; IGHD2
Tractability: Small molecule: a structure with a bound ligand is known; it has a binding pocket of medium quality. Antibody: UniProt places it where antibodies can reach, with high confidence; its Gene Ontology location is reachable by antibodies, with high confidence; UniProt predicts a signal peptide or a membrane-spanning region.
Gene: Protein-coding gene on chromosome 17 (63,917,200 to 63,918,839, reverse strand). Ensembl gene ENSG00000259384.
Subcellular location: Secreted
Pathways (Reactome):
Immune System: Growth hormone receptor signaling; Prolactin receptor signaling
Metabolism of proteins: Synthesis, secretion, and deacylation of Ghrelin
Gene Ontology:
Molecular function: cytokine activity; growth factor activity; growth factor receptor binding; growth hormone activity; growth hormone receptor binding; prolactin receptor binding; protein binding; hormone activity
Biological process: bone maturation; cell surface receptor signaling pathway via JAK-STAT; cell surface receptor signaling pathway via STAT; cytokine-mediated signaling pathway; growth hormone receptor signaling pathway; growth hormone receptor signaling pathway via JAK-STAT; positive regulation of D-glucose transmembrane transport; positive regulation of insulin-like growth factor receptor signaling pathway; positive regulation of multicellular organism growth; positive regulation of phosphatidylinositol 3-kinase/protein kinase B signal transduction; positive regulation of receptor internalization; positive regulation of receptor signaling pathway via JAK-STAT; response to estradiol; animal organ development; positive regulation of MAPK cascade; response to nutrient levels
Cellular component: extracellular matrix; extracellular region; growth hormone receptor complex; endosome lumen; cytoplasm; endomembrane system; vesicle
Genetic constraint (gnomAD): Loss-of-function variants: 13 observed, 24.66 expected, observed/expected ratio (o/e) 0.53, 90% interval 0.34 to 0.84. The upper end of that interval is the gene's LOEUF score, 0.84, which puts it in group 3 of 6, group 1 being the genes least tolerant of losing a copy. Missense variants: 294 observed, 280.95 expected, observed/expected ratio (o/e) 1.05, 90% interval 0.95 to 1.15. Synonymous variants: 126 observed, 119.64 expected, observed/expected ratio (o/e) 1.05, 90% interval 0.91 to 1.22.
Homologues: Orthologues: pig GH1 (67% identical), dog GH1 (66% identical), rabbit GHB1 (66% identical), mouse Gh (65% identical), rat Gh1 (64% identical), guinea pig Gh1 (63% identical), tropical clawed frog gh1 (50% identical), tropical clawed frog gh2 (42% identical), zebrafish gh1 (36% identical). Paralogues in human: GH2 (93% identical), CSH1 (85% identical), CSH2 (85% identical), CSHL1 (81% identical), PRL (24% identical).
Diseases named in the same sentence as GH1 in open-access papers:
GH1 is named in the same sentence as 706 diseases in open-access papers, as found by Europe PMC text mining. Sharing a sentence is not in itself a finding about the gene and the disease. The quoted sentences say what the papers report.
acromegaly (450 papers, 2006 to 2026). Acromegaly is an acquired disorder related to excessive production of growth hormone (GH) and characterized by progressive somatic disfigurement (mainly involving the face and extremities) and systemic manifestations. "The search term was “(Acromegaly OR Growth hormone OR Insulin-like growth hormone-1 OR Prolactin) AND (Hypercalcemia)”." (PMID 33933067, 2021). "Acromegaly is a disease characterized by the hypersecretion of growth hormone (GH)/insulin-like growth hormone-1 (IGF-1), typically as a result of a benign pituitary adenoma." (PMID 31879842, 2020). "To produce a zebrafish acromegaly model, we performed the overexpression of tilapia GH instead of zebrafish gh1 to be able to differentiate between endogenous and exogenous GH gene expression." (PMID 30336646, 2018). "On the other hand, endogenous zebrafish gh1 gene expression was significantly reduced in acromegaly larvae and one-year-old acromegaly brain (including pituitary gland), likely due to a negative feedback loop involving GH excess." (PMID 30336646, 2018). "Although gene expression of GH1 was greater in cats with acromegaly than in controls, this was not statistically significant (median control vs HST was 3.1 vs 6.2; Mann–Whitney U test, P = 0.071)." (PMID 30620005, 2019). "Using qPCR, we did not detect endogenous zebrafish gh1 in other organs in WT or the acromegaly model." (PMID 30336646, 2018).
pituitary adenomas (265 papers, 2008 to 2026). "Single‐cell data from four GH‐type pituitary adenomas were collected from public databases to explore ITH in GH1 gene expression." (PMID 40852938, 2025).
Obesity (199 papers, 2006 to 2026). Accumulation of substantial excess body fat. "Obesity-related genes were retrieved in the Digsee database and the top 15 obesity-related genes were selected as disease genes (Adipoq, Igf1, Fto, Hsd11b1, Tnf, Gh1, Mc4r, Lep, Pparg, Il6, Crp, Lepr, Pomc, Lpl, and Ghr1)." (PMID 31060494, 2019). "The network of cardiometabolic proteins in obesity showed that the strongly higher-expressed LEP in the obese group interacts with the less-expressed GHRL and more-expressed GH1." (PMID 38732002, 2024).
adenoma (116 papers, 2006 to 2025). A neoplasm arising from the epithelium. "The Klk1 gene was also observed to be associated with prolactin-secreting cells within human Gh1-secreting adenomas." (PMID 35180880, 2022).
Hypoglycemia (111 papers, 2007 to 2026). A decreased concentration of glucose in the blood. "Our patient, who had the c.615C>G variation in the GH1 gene, had a history of prolonged labor and hypoglycemia during the infantile period." (PMID 37948564, 2023).
pituitary tumor (83 papers, 2010 to 2025). A benign or malignant neoplasm affecting the pituitary gland. "Lats1, a tumor suppressor homolog, affects the promoter activity of cellular Gh1 and Prl in pituitary tumors, and Lats1 is involved in the regulation of prolactin expression." (PMID 36555554, 2022).
hypopituitarism (77 papers, 2011 to 2026). A condition of diminution or cessation of secretion of one or more hormones from the anterior pituitary gland. "In conclusion, we report progression of isolated growth hormone deficiency due to a germline GH1 variant to combined pituitary hormone deficiency followed by hypercortisolism due to an ACTH-secreting macroadenoma with a somatic variant in USP8 in the same patient." (PMID 35029852, 2022). "In this paper we describe variants in GH1, SOX3 and TGIF1, three genes that are already associated with hypopituitarism." (PMID 34440302, 2021). "The GH1 variant c.171delT (p.Phe57Leufs*43) has never been described in association with hypopituitarism, either in OMIM or in Genecards." (PMID 34440302, 2021).
breast carcinoma (61 papers, 1997 to 2026). "Tamoxifen binds to the estrogen receptor instead of the endogenous growth hormone 17β-estradiol, leading to an inhibition of breast cancer cell proliferation and resulting in apoptosis." (PMID 38732206, 2024).
growth disorders (43 papers, 2012 to 2025). "Disruptions in the intricate GH signaling pathway, often due to mutations in the GH1 gene, can lead to various growth disorders." (PMID 41614776, 2025). "Emerging evidence supports integrating next-generation sequencing (NGS) into the diagnostic work-up for growth disorders to identify GH1 and other relevant gene variants." (PMID 41019338, 2025). "The spectrum of GH1 mutations leading to growth disorders underscores the critical importance of various structural and functional aspects of the growth hormone protein." (PMID 41614776, 2025). "GH1 is a commonly measured biomarker in the diagnosis and during treatment of growth disorders, but because of the occurrence of many closely related isoforms, its quantification is far from straightforward." (PMID 35838770, 2022). "All these variants were identified in genes already associated with growth disorders: PROKR2 (N = 2), PTPN11 (N = 6), ANKRD11 (N = 1), NPR2 (N = 1), NF1 (N = 1), ACAN (N = 1), GH1 (N = 1), FBN1 (N = 1), COMP (N = 1), IGF1R (N = 1), ARID1A (N = 1), and CASR (N = 1)." (PMID 37605180, 2023). "The human growth hormone GH1 (22 kDa) is a commonly measured biomarker for diagnosis and during treatment of growth disorders, but its quantification by ligand binding assays may be compromised by the occurrence of a number of isoforms." (PMID 35838770, 2022).
growth failure (33 papers, 2006 to 2026). "Mutations in the GH1 gene can lead to isolated GH deficiency (IGHD), a rare disorder characterized by growth failure and severe short stature." (PMID 41561060, 2025).
depression (32 papers, 2010 to 2026). "During the process of epileptogenesis, the upregulation of GH was detected, and also GH1 downregulation can be a result of epilepsy, which can cause depression." (PMID 37252132, 2023). "Missingness increased only for some items with poorer health status: subjects having been hospitalized in the year had higher proportion of missing data for PF1, GH3 and GH5; those with chronic disease(s) for PF9; and subjects with depression as classified by the CES-D for GH1, VT1 and MH4." (PMID 20128899, 2010). "Meanwhile, the abundance of GH1 and GH4 genes displayed a negative correlation with Muribaculaceae and a positive association with Faecalibaculum_rodentium and anxiety/depression-like behaviors." (PMID 39599623, 2024).
type 2 diabetes (32 papers, 2008 to 2025). "Anti-pituitary antibodies are observed in conjunction with type-2 diabetes and GH1 is one of the autoantigens." (PMID 24988487, 2014).
type 1 diabetes (24 papers, 2013 to 2025). "Previous studies have suggested that HOXB3, GH1 and KIR2DL4 are involved in autoimmune disease such as Thyroid-associated orbitopathy (TAO), Type 1 diabetes (T1DM), and Systemic lupus erythematosus (SLE)." (PMID 33384687, 2020).
dwarfism (18 papers, 2014 to 2024). "Interestingly, the dwarfism growth-hormone deficiency gene (GH1) was identified in this region." (PMID 34461820, 2021).
melanoma (18 papers, 2013 to 2025). A malignant, usually aggressive tumor composed of atypical, neoplastic melanocytes. "Both B16-F10 mouse melanoma and SK-MEL-30 human melanoma cells express Ghr and Igf-1r RNA, while SK-MEL-30 also expressed GH1 and IGF-1 transcripts." (PMID 33291663, 2020). "In addition, the genes EBI3, GH1, SOX9, RET, and SPRY2 are also good candidates for HH-GLI targets but exhibited a less uniform expression pattern in these melanoma cell lines." (PMID 36139698, 2022).
panhypopituitarism (14 papers, 2018 to 2026). Insufficient production of all the anterior pituitary hormones. "The molecular analysis was carried out by new generation sequencing (NGS) of the candidate genes for panhypopituitarism (PROP1, POU1F1, GH1, GHRH, GHRHR, HESX1, PROKR2)." (PMID 34814931, 2021).
epilepsy (9 papers, 2018 to 2025). A brain disorder characterized by episodes of abnormally increased neuronal discharge resulting in transient episodes of sensory or motor neurological dysfunction, or psychic dysfunction. "The Chronic time-point has just a single mRNA, Gh1, in this heatmap, indicating that the 23 shortlisted miRNAs may be more active/have more impact at the epileptogenic time-points prior to epilepsy establishment." (PMID 38961125, 2024).
celiac disease (8 papers, 2005 to 2026). An autoimmune genetic disorder with an unknown pattern of inheritance that primarily affects the digestive tract. "GH1 codes for human growth hormone, and growth impairment is observed in celiac disease in conjunction with anti-pituitary antibodies." (PMID 24988487, 2014).
colorectal cancer (8 papers, 2012 to 2024). A primary or metastatic malignant neoplasm that affects the colon or rectum. "Studies of the functional SNP rs2665802 (in GH1) have found associations between its minor allele and lower colorectal cancer risk and mortality risk in females." (PMID 22253814, 2012). "The allele has also been associated with lower colorectal cancer and mortality risk in females, though the null findings observed for the other measures of physical capability would suggest that rs2665802 (GH1) does not substantially influence measures of physical capability." (PMID 22253814, 2012).
pancreatic cancer (8 papers, 2017 to 2025). "Genetically modified BECs might, however, secrete the recombinant protein in both luminal and abluminal directions, which in some cases might be a problem, as some neurotropic factors, such as growth hormone 1, have been shown to cause pancreatic cancer in monkeys when present in the circulation." (PMID 41382141, 2025). "Besides, we have introduced two biologically relevant triplets, namely Klk1 and {Gh1, Cst3} and Lamc2 and {Dhps, Ccr7}, which may be specifically involved in the onset of pancreatic cancer." (PMID 35180880, 2022).
microcephaly (7 papers, 2012 to 2026). A congenital or acquired developmental disorder in which the circumference of the head is smaller than normal for the person's age and sex. "Infection with gH1 genotype was also associated with a three-fold increased risk of neurological dysfunction and microcephaly (P < 0.05)." (PMID 31705022, 2019).
Short stature (6 papers, 2015 to 2022). A height below that which is expected according to age and gender norms. "In this study, we performed for the first time molecular analysis of the GH1 gene in a cohort (n = 186) of Polish children and adolescents with short stature, suffering from growth hormone deficiency (GHD) or idiopathic short stature (ISS), and a control cohort (n = 178)." (PMID 32338337, 2020). "Monogenic causes of short stature which are associated with a low serum IGF-I level and normal or high GH levels could comprise the defects of GH1 (bioinactive GH), GHSR (ghrelin receptor), GHR (GH receptor), STAT5B, IGF1, and IGFALS." (PMID 26777041, 2015).
influenza (5 papers, 2013 to 2024). An acute viral infection of the respiratory tract, occurring in isolated cases, in epidemics, or in pandemics; it is caused by serologically different strains of viruses (influenzaviruses) designated A, B, and C, has a 3-day incubation period, and usually lasts for 3 to 10 days. "The 2009 pandemic strain HA globular head domain (gH1), which contains many of the known influenza-neutralizing epitopes, is covalently linked to VLPs derived from the bacteriophage Qβ." (PMID 24204639, 2013). "The gH1-Qbeta vaccine is a novel pandemic-influenza vaccine produced by covalently linking the globular head domain of haemagglutinin (gH1) from A/California/07/09 produced in E. coli to VLPs from the bacteriophage Qbeta21." (PMID 30573748, 2018). "This capacity of the gH1-Qbeta vaccine to preferentially elicit IFN-γ is seen in a subset of individuals whose pre-existing influenza-specific cytokine responses were characterized by the T helper type 2 (Th2) cytokines IL-5 and IL-13." (PMID 30573748, 2018). "Although the neutralizing antibody titers and clinical scores were comparable a significantly lower influenza titer in ferret nasal lavages was observed in the Panvax group compared to the alum-adjuvanted gH1-Qβ group." (PMID 24204639, 2013). "The contribution of these CD4+ T cell mediated anti-viral activities in directly controlling influenza infection following vaccination with the gH1-Qβ vaccine require further studies for investigation." (PMID 24204639, 2013). "The ability of the gH1-Qbeta VLP vaccine to influence the quality of the cytokine response was further emphasized in specific individuals whose pre-existing influenza responses were characterized by a higher level of the Th2 cytokines IL-5 and IL-13 over the Th1 cytokine IFN-γ." (PMID 30573748, 2018). "Further studies including a planned human challenge study with the gH1-Qbeta VLP vaccine will reveal any protective capability against influenza infection as well as the role of T-cell responses in protection and allow validation of the gene signatures identified here." (PMID 30573748, 2018). "Overall, this study showed that both non-adjuvanted and adjuvanted formulations of the gH1-Qbeta vaccine induced influenza-specific CD4+ and CD8+ T-cell responses and influenza-specific induction of a number of cytokines including anti-viral IFN-γ." (PMID 30573748, 2018). "In summary, immunization of mice with 10 μg of adjuvanted gH1-Qβ (3.7 μg globular HA content) compared favorably with 1.5 μg of unadjuvanted Panvax (0.7 μg globular HA content) in terms of HAI and neutralizing antibody titers, and achieved control of influenza in the lung following pH1N1 challenge." (PMID 24204639, 2013).
isolated growth hormone deficiency (5 papers, 2018 to 2026). "Congenital isolated growth hormone deficiency (IGHD) type 1b is an autosomal recessive genetic condition caused by mutations of growth hormone (GH)-1 or the growth hormone releasing hormone receptor (GHRH-R) genes." (PMID 29537382, 2018).
viral infection (4 papers, 2012 to 2025). "In order to address the hypothesis that gH1 and/or gH4 can affect viral infection of PBMC, we first infected PBMC with EHV-1 and EHV-4 strains and analyzed the percentages of infected cells by flow cytometry." (PMID 22909178, 2012). "Even with GH1 overexpression leading to a decrease in cellular PI4P content, the remaining PI4P is adequate for supporting the establishment of RSMV VFs and viral infection." (PMID 40834074, 2025). "Finally, we found that HeLa, MDBK, PBMC, EC and 293 cells can be infected with parental and mutant viruses with similar efficiencies and that viral infection was independent of gH1 or gH4, respectively (data not shown)." (PMID 22909178, 2012).
bladder cancer (3 papers, 2024 to 2026). "For further validation, Kaplan–Meier survival plots with GHR, GH1, IGF-1 receptor (IGF1R), or IGF1 as the reference gene were generated from TCGA database, including 405 patients with bladder cancer." (PMID 40806252, 2025).
coronary artery disease (3 papers, 2017 to 2023). "Six genes (ABCB1, PLAT, ACE, GH1, PECAM1, and RGS9) known to predispose people to coronary artery disease occur in the cn-LOH regions identified." (PMID 28120895, 2017).
Kowarski syndrome (3 papers, 2019 to 2025). "Kowarski syndrome results from autosomal-dominant mutations in GH1, that produce biologically inactive GH with reduced affinity for the GH receptors (GHRs) and GH-binding proteins (GHBPs)." (PMID 40868191, 2025). "The GH1 gene is located on chromosome 17q22.24, and its mutations are responsible for several distinct forms of IGHD, including IGHD type IA, IGHD type IB (also associated with GHRHR mutations), IGHD type II, and Kowarski syndrome (also known as “bioinactive GH syndrome”)." (PMID 40868191, 2025).
Fanconi anemia (2 papers, 2011 to 2021). Fanconi anemia (FA) is a hereditary DNA repair disorder characterized by progressive pancytopenia with bone marrow failure, variable congenital malformations and predisposition to develop hematological or solid tumors. "There were 4 SNPs in the DNA repair gene FANCM (Fanconi anemia, complementation group M) and 2 SNPs in the growth and hormone gene GH1 that were significantly associated with OS after correction for multiple tests." (PMID 21619704, 2011).